CCND1 (cyclin D1)
Diseases named in the same sentence as CCND1 in open-access papers (continued):
Sharing a sentence is not in itself a finding about the gene and the disease.
hepatocellular carcinoma (continued). "BBR inhibits cyclin D1 expression in human hepatoma cells both in vitro and in vivo in a dose- and time-dependent manner." (PMID 34885950, 2021). "Critical genes encoded by this region include CCND1, FGF3, FGF4, which are involved in cell-cycle regulation and tumor cell proliferation in oral squamous cell carcinoma, hepatocellular carcinoma, and ESCC11,54–56." (PMID 34285259, 2021). "In HepG2 human hepatoma cells, berberine suppressed cyclin D1 expression, which inhibited cell proliferation." (PMID 33806918, 2021). "CCND1, CDK4, MAPK1, CDKN1A, and E2F2 genes are linked to the development of hepatocellular carcinoma." (PMID 33959508, 2021). "As a consequence of PDGFRαD842V overexpression, the downstream and target genes phosphor-Akt (Thr308), cyclin D1 and c-myc were upregulated in TG hepatomas compared with WT tumors on IHC staining." (PMID 32489479, 2020). "Up-regulation of JCAD inhibits the ability of LATS2 to phosphorylate YAP, thus elevating CCND1 and Gli2 expression to promote hepatoma cell proliferation." (PMID 32493490, 2020). "As a proto-oncogene, CCND1 can promote DNA synthesis, cell proliferation, cell colonization, and hepatoma formation (Wu, Lan & Liu, 2019)." (PMID 32095323, 2020). "One recent study showed that autophagy can degrade cyclin D1 (CCND1) and arrest the cell cycle in the G1 phase to inhibit the proliferation of hepatocellular carcinoma cells." (PMID 32683410, 2020). "Accordingly, the Cyclin D1-dependent activation of Smad2/3 and Smad4 is also evidenced in hepatocellular carcinoma (HCC) patients and predicts disease progression." (PMID 33317149, 2020). "In one study, STAT3 inhibition downregulated the expression of Bcl-xL, cyclin D1 and survivin, and induced apoptosis in a hepatocellular carcinoma xenograft model." (PMID 32872659, 2020). "Like IL-6 related markers and chemokines/cytokines, KI67 and Cyclin D1 dysregulation is an indicator of many different liver conditions including hepatocellular carcinoma, nonalcoholic fatty liver disease, chronic alcohol exposure, and liver injury." (PMID 33250767, 2020). "The raw data is available at Figshare: Fang, Ye-ying (2019): Downregulation of miR-193a-3p is involved in the pathogenesis of hepatocellular carcinoma by targeting CCND1 Peer J #40214." (PMID 32095323, 2020). "Besides, Cyclin D1 and the autophagic degradation machinery are together linked to hepatocellular carcinoma (HCC) tumorigenesis." (PMID 33317149, 2020). "Several studies reported that inhibition of the STAT3 signaling pathway reduced the expression of cyclin D1 and enhanced the drug sensitivity of the cancer cells, including gastric carcinoma, cholangiocarcinoma, bladder cancer and hepatocellular carcinoma." (PMID 32872659, 2020). "The present study aimed to compare cyclin D1 (CCN D1) gene expression in hepatocellular carcinoma cell line (HUH7) when it is treated with nanomicelle curcumin and sorafenib." (PMID 31998463, 2019). "A nuclear cyclophilin isoform, cyclophilin J, is upregulated in many hepatocellular carcinomas and facilitates cell cycle progression in part through cyclin D1 elevation." (PMID 31406003, 2019). "Recent findings imply that abnormal expression of cyclin D1 probably has a remarkable effect on the growth of human hepatoma as well as other carcinomas." (PMID 31998463, 2019). "The previous research pointed out that dovitinib downregulates the p-STAT3 and subsequently reduced the levels of expression of STAT3-related proteins Mcl-1, survivin, and cyclin D1 in a time-dependent manner in human hepatocellular carcinoma (HCC)." (PMID 31485222, 2019). "(2013) recently demonstrated that the miR‐590‐5P directly binds 3′ UTR of S100A10 to inhibit its expression which was concomitant with downregulation of CCND1 in HepG2 hepatocellular carcinoma cells." (PMID 30009399, 2018).
hepatocellular carcinoma (continued). "However, this relationship is less apparent in human hepatocellular carcinoma (HCC), for which only CCND1 870G>A polymorphism has been suggested as a risk factor of HCC." (PMID 28415588, 2017). "Overexpression of proteins involved in cell cycle progression, e.g. Cyclin D1 in HCC patients and hepatoma cell lines, has been found to be associated with cancer development and progression." (PMID 27518192, 2016). "The suppression of ARID2 expression in hepatoma cells facilitated G1/S transition associated with transcriptional upregulation of E2F1, cyclin D1, and cyclin E1, induction of CDK4, and phosphorylation of Rb." (PMID 27351279, 2016). "While berberine significantly reduced proliferation of xenografted hepatoma, the expression of Cyclin D1 in hepatoma xenograft was in parallel inhibited." (PMID 27854312, 2016). "Berberine exhibits dose- and time-dependent inhibition on Cyclin D1 expression in human hepatoma cell HepG2." (PMID 27854312, 2016). "It was noticed that berberine can suppress the expression of Cyclin D1 in different hepatoma cell lines including HepG2 and MHCC97L." (PMID 27854312, 2016). "Intestine-specific homeobox (ISX), a newly identified proto-oncogene, regulates cell proliferation and drives hepatocellular carcinoma (HCC) formation via cyclin D1 upregulation under stimulation by proinflammatory cytokines such as IL-6." (PMID 27175585, 2016). "A Gnmt knockout mouse model of hepatocellular carcinoma has shown that genes related to the Wnt pathway (e.g., Ctnnb1, Ccnd1, and Myc) were up-regulated, indicating that GNMT is a tumor suppressor gene for liver cancer." (PMID 27469031, 2016). "PIN1 overexpression has also been shown to up-regulate cyclin D1 and β-catenin in hepatocellular carcinomas (HCC)." (PMID 27258148, 2016). "Consistently, we observed reduced expression of Cyclin D1 in hepatoma cells with berberine treatment." (PMID 27854312, 2016). "In conclusion, we observed that berberine exhibits dose- and time-dependent inhibition on Cyclin D1 expression in human hepatoma cells." (PMID 27854312, 2016). "In our study, we found a rapid suppression action of berberine on Cyclin D1 expression in human hepatoma cells HepG2, and berberine promotes an ubiquitination-dependent proteolysis of Cyclin D1 in HepG2 cells." (PMID 27854312, 2016). "The significant increase of beta-catenin, NFkB, and cyclin D1 depicts one of the mechanisms curcumin works in hepatoma cells." (PMID 26515460, 2015). "Possible ways of action in hepatocellular carcinoma cells are the inhibition of the NFkB-, and the Wnt/beta-catenin-pathway, resulting in cyclin D1 decrease." (PMID 26515460, 2015). "A previous study conducted in hepatoma cell lines has found elevated level of cyclin D1 in response to HNF1A inactivation." (PMID 25793983, 2015). "In a study on hepatocellular carcinoma, CCND1 amplification was embedded within a “chromothriptic” event on chromosome 11." (PMID 24476156, 2014). "The results indicated that the effect of Kin17 in promoting the proliferation of hepatocellular carcinoma cells correlates with the expression of cyclin D1 and p27Kip1." (PMID 25120685, 2014). "The aim of this study was to investigate the methylation status of fragile histidine triad (FHIT) and the effects of FHIT on cell growth and cyclin D1 expression in hepatoma cells." (PMID 24396396, 2014). "For instance, miR-15b induced cell cycle arrest at G0/G1 phase by targeting cyclin E in glioma cells; miR-16 induced G1 arrest partially by targeting cyclin D1; miR-122a can modulate cyclin G1 expression in human hepatocellular carcinoma-derived cell lines." (PMID 24984770, 2014). "Suppression of cyclin D1 has also been demonstrated to inhibit tumor cell growth in human hepatocellular carcinoma and colonic adenocarcinoma." (PMID 24303084, 2013). "Taken together, our finding suggests that miR-520b targeted MEKK2 and cyclin D1 are involved in the tumorigenicity of hepatoma cells in vitro and in vivo." (PMID 22319632, 2012).
hepatocellular carcinoma (continued). "In conclusion, miR-520b is able to inhibit the growth of hepatoma cells by targeting MEKK2 or cyclin D1 in vitro and in vivo." (PMID 22319632, 2012). "The aim of our project was to evaluate the SHP levels in typical and fibrolamellar hepatocellular carcinoma with respect to the levels of one of the cell cycle regulators, cyclin D1." (PMID 22292081, 2012). "Then, we chose two of target genes of miR-520b, such as MEKK2 and cyclin D1 which play important roles in the cell cycle and the cell growth, to demonstrate the mechanism of miR-520b in regulation of the growth of hepatoma cells." (PMID 22319632, 2012). "We found that the transfection with miR-520b in hepatoma cells led to the downregulation of cyclin D1 and decreased the levels of p-Rb." (PMID 22319632, 2012). "We restored miR-99a in 786–0 cells and found that the expression of p-p70S6K, p-4E-BP1, cyclin D1, cyclin D3 and cyclin E are really downregulated, consistent with the previous reports in hepatocellular carcinoma." (PMID 23173671, 2012). "FGF19, a fibroblast growth factor, together with CCND1, was recently reported to a major driver oncogene in hepatocellular carcinoma." (PMID 22761904, 2012). "Our data showed that silencing either MEKK2 or cyclin D1 was able to inhibit the growth of hepatoma cells in vitro." (PMID 22319632, 2012). "MTT assays showed that the enforced expression of miR-520b dramatically inhibited the proliferation of hepatoma cells and the overexpression of cyclin D1 was able to rescue miR-520b-inhibited proliferation of HepG2 and H7402 cells." (PMID 22319632, 2012). "Perturbations in Cyclin D1 and its impact on hepatocarcinoma has been widely observed in 30 different hepatoma types." (PMID 22035408, 2011). "Recent studies have highlighted the importance of miR-195 that target cyclin D1 which regulate the G1-S phase transition, while ectopic expression of miR-101 dramatically suppressed the ability of hepatoma cells to form colonies." (PMID 22035408, 2011). "Two of the 59 inverse miRNA:mRNA target pairs we identified have been validated: miR-21:NFIB (an oncogenic interaction) in leukemia cells and miR-195:CCND1 (a tumor-suppressive interaction) in hepatocellular carcinoma." (PMID 21375733, 2011). "Micro RNAs whose target is Cyclin D1 such as miR-195a and miR-101-1 that is required for growth of hepatoma cells was drastically affected." (PMID 22035408, 2011). "In hepatocellular carcinomas, cytoplasmic cyclin D1 appeared to significantly correlate with prognostic factors like intrahepatic metastasis." (PMID 17375037, 2007). "The 35-kDa cyclin D1 is overexpressed in several types of carcinomas and, therefore, suggested to play an important role in tumorigenesis and tumor progression including hepatocellular carcinoma." (PMID 16823072, 2006). "Co-treatment with these two drugs led to G1 growth arrest, accompanied by down-regulation of cyclin D1 and up-regulation of p21WAF-1, and accumulation of hypophosphorylated retinoblastoma protein in hepatoma cells." (PMID 10360647, 1999). "Similarly, in hepatocellular carcinoma, the development of lenvatinib resistance is closely associated with the aberrant activation of the AHR-AREG-EGFR-ERK1/2-Cyclin D1 signaling axis." (PMID 41585883, 2025). "Similarly, HT has been shown to inactivate AKT and NF-κB, leading to a reduced expression of Cyclin D1, c-Myc, and Bcl-2 in hepatocellular carcinoma models." (PMID 40725203, 2025). "Overexpression of ROR‐α‐1 significantly inhibits the proliferation, migrationand invasion capabilities of HCC (hepatocellular carcinoma) cells and downregulates the protein levels of c‐Myc and Cyclin D1, suggesting a tumour‐suppressive role for ROR‐α‐1 in liver cancer cells (PMID: 32058275)." (PMID 38568083, 2024). "However, overexpression of Cyclin D1 at the same time as overexpression of WISP1 restored the proliferative activity of hepatoma cells." (PMID 39763353, 2024).
hepatocellular carcinoma (continued). "Our experiments revealed that the knockdown of SPP1 in both hepatocellular carcinoma cell lines led to a significant reduction in the expression of C‐Myc and Cyclin‐D1, indicating that SPP1 may promote tumour development through the myc signalling pathway." (PMID 38568083, 2024). "A possible explanation could be the appearance of oleic acid, in our characterization, which was proven earlier as a defeater of hepatocellular carcinoma progression through mediating cyclin D1 expression." (PMID 38469406, 2024). "To confirm that Cyclin D1 protein level regulates the ubiquitination-proteasomal degradation in hepatoma cells, we first confirmed whether Cyclin D1 interacts with Ub in Hep3B and HCCLM3 cells." (PMID 39763353, 2024). "HuR targets include invasive and metastatic RNAs (e.g., MMP-9, MTA1, and uPA), angiogenic RNAs (e.g., VEGF-1 and HIF-1), and cell proliferative RNAs (e.g., EGF, cyclin A, cyclin B1, cyclin E, and cyclin D1), through which it can influence hepatocellular carcinoma progression." (PMID 37540723, 2023). "And MCM7 was found to promote hepatocellular carcinoma through cyclin D1-dependent signaling." (PMID 37531195, 2023). "Moreover, cyclin D1, another important regulator of cell cycle progression, is identified as a direct target gene of MafB in hepatocellular carcinoma." (PMID 36750911, 2023). "Additionally, CCND1 is also highly expressed in hepatocellular carcinoma tissues, and it is reported that LINC00152 regulates cancer cell proliferation by miR-193a/b-3p/CCND1 axis." (PMID 36760720, 2023). "Furthermore, reduced expression of cyclin D1, cyclin D2 and cdk4 leading to cell cycle arrest in a hepatocellular carcinoma (HCC) cell line have been reported after treatment with canagliflozin." (PMID 35328527, 2022). "Additionally, the extract triggered the arrest of the G0/G1 phase of the cell cycle and upregulated the protein expression of p27/Kip and p21/Cip, with a decrease in cyclin D1 expression in hepatocellular carcinoma cells." (PMID 34316277, 2021). "CDK2, CDK4, CCNB1 and CCND1 can accelerate the cell cycle moving from G1 to S phase and then promote the proliferation of various cell types including mouse embryonic fibroblasts, mouse neural progenitor cells and human hepatocellular carcinoma." (PMID 34438874, 2021). "miR-193a-3p could suppress proliferation and promote apoptosis by targeting cyclin D1 in hepatocellular carcinoma cells." (PMID 33628829, 2021). "Furthermore, MAPK1, E2F2, CDK4, CDKN1A, CCND1 were found key target genes of hepatocellular carcinoma pathway." (PMID 33959508, 2021). "An oleanane-type saponin oleiferasaponin C6 from Camellia oleifera seeds was found to induce cell cycle arrest at the G0/G1 phases through regulating p21, cyclin-dependent kinase 4 (CDK4) and cyclin D1 in human promyelocytic leukemia HL-60 cells and hepatocellular carcinoma BEL-7402 cells." (PMID 33802884, 2021). "LINC00467, a greatly concerned LncRNA in cancer-related research recently, has been demonstrated to promote lung adenocarcinoma proliferation by sponging miR-20b-5p to activate CCND1 expression, regulate hepatocellular carcinoma progression by modulating miR-9-5p/PPARA expression." (PMID 33996559, 2021). "Quininic acid was shown to significantly suppress the invasion of a rat ascites hepatoma in vitro and promoted apoptosis in oral cancer cells by downregulating the expression of anti-apoptotic genes and attenuating the expression of cyclin D1 and Akt signalling pathway." (PMID 33371199, 2020). "However, overexpression of ATF3 increases DNA synthesis and cyclin D1 mRNA expression in the Hepa 1–6 mouse hepatoma cells." (PMID 32922364, 2020). "However, overexpression of ATF3 increases cyclin D1 mRNA expression in the Hepa 1–6 mouse hepatoma cells." (PMID 32922364, 2020). "Cyclin D1, associated with CDK4, controls glucose metabolism in hepatic carcinoma cells." (PMID 32709889, 2020).
hepatocellular carcinoma (continued). "The most significantly bioactive compound berberine from CR could suppress Cyclin D1 expression via proteasomal degradation in human hepatoma cells." (PMID 31649545, 2019). "Our previous study showed that cyclin D1 could down-regulate NTCP expression in HBV-related hepatocellular carcinoma." (PMID 31179847, 2019). "Moreover, miR-193b-3p was able to regulate proliferation, migration, and invasion in human hepatocellular carcinoma cells by suppressing CCND1 and ETS1." (PMID 31262974, 2019). "Cyclin D1 levels were also decreased in hepatocellular carcinoma cells expressing TYRO3 siRNA." (PMID 30501104, 2018). "In hepatocellular carcinoma, FoxM1 could regulate cell cycle arrest, and the expression of cyclin B1, p27, and cyclin D1 was all changed in FoxM1 knock out MHCC-97H cells." (PMID 29554906, 2018). "Both IL-20 and cyclin D1 mRNA were expressed in three different human hepatoma cell lines." (PMID 29242565, 2017). "As well, Cyclin D1 was potently inhibited in berberine-treated hepatoma xenograft." (PMID 27854312, 2016). "Furthermore, down-regulation of URG4 was shown to suppress cyclin D1 expression and cell proliferation in HepG2 hepatocellular carcinoma cells, further supporting our results." (PMID 27443843, 2016). "Although the mechanism of how these limonoids interfere with the NF-κB signaling pathway has to be investigated in more detail, our results indicate that TR4 and TR9 reduce NF-κB activity in hepatoma cells, resulting in decreased expression of NF-κB targets (Cyclin D1, Bcl2 or A20)." (PMID 27518192, 2016). "In the current study, we showed that WM130 could reduce the protein levels of β-catenin and its target gene Cyclin D1 in hepatoma cells." (PMID 27783993, 2016). "To determine if inhibition of berberine on Cyclin D1 expression in hepatoma cells undergoes the same mechanism, we issued a quantitative real-time polymerase chain reaction (qPCR) analysis to quantify the Cyclin D1 mRNA transcripts in HepG2 cells exposed to berberine." (PMID 27854312, 2016). "As ARID2 induces cyclin D1 and cyclin E1 repression, thereby inhibiting the proliferation of hepatoma cells, this protein may be critical for the suppression of HCC tumorigenesis in vivo." (PMID 27351279, 2016). "We observed that berberine could suppress both in vitro and in vivo expression of Cyclin D1 in hepatoma cells." (PMID 27854312, 2016). "It was observed that berberine could suppress both in vitro and in vivo expression of Cyclin D1 in hepatoma cells." (PMID 27854312, 2016). "However, few studies have focused on the clinical relevance of MIF and cyclin D1 expression in hepatocellular carcinoma cells (HCCs)." (PMID 25015194, 2014). "Thus, our data suggested the Akt/GSK-3β/cyclin D1 signaling pathway mediated the function of βKlotho in hepatoma cells proliferation and hepatocarcinogenesis." (PMID 23383245, 2013). "In contrast, an inverse correlation has been seen between p57KIP2 and cyclin D1 expression in hepatocellular carcinoma, whereas such association has not been identified in ovarian cancer." (PMID 23580324, 2013). "Finally, we demonstrate a negative correlation between the expression of SHP and one of the most potent cell cycle regulator, cyclin D1, in high grade hepatocellular carcinomas." (PMID 22292081, 2012). "Silencing of MEKK2 or cyclin D1 was able to inhibit the growth of hepatoma cells in vitro and in vivo, which is consistent with the effect of miR-520b overexpression on the growth of hepatoma cells." (PMID 22319632, 2012). "To explore whether miR-520b targeted MEKK2 or cyclin D1 is responsible for the inhibition of the growth of hepatoma cells, we examined the effects of knockdown of target genes on the growth of hepatoma cells." (PMID 22319632, 2012). "Thus, our data suggest that cyclin D1 overexpression rescues the inhibition of hepatoma cell growth mediated by miR-520b." (PMID 22319632, 2012).